AIFM1 (apoptosis inducing factor mitochondria associated 1)
Diseases named in the same sentence as AIFM1 in open-access papers (continued):
Sharing a sentence is not in itself a finding about the gene and the disease.
psoriasis (2 papers, 2021 to 2025). An autoimmune condition characterized by red, well-delineated plaques with silvery scales that are usually on the extensor surfaces and scalp. "Pharmacological inhibition of NADPH oxidases/NAMPT/PARP/AIFM1 axis decreased the expression of pathology-associated genes in human organotypic 3D skin models of psoriasis." (PMID 34748530, 2021). "An abnormal increase in visfatin/NAMPT and poly(ADP-ribose) (PAR) polymerase (PARP) activity, along with the nuclear translocation of AIFM1, was observed in lesional skin from psoriasis patients." (PMID 41002974, 2025). "Consistently, an aberrant induction of NAMPT and PARP activity, together with AIFM1 nuclear translocation, was observed in lesional skin from psoriasis patients." (PMID 34748530, 2021). "Strikingly, a higher percentage of keratinocytes showing nuclear AIFM1 staining was found in lesional skin from psoriasis patients compared with healthy skin." (PMID 34748530, 2021). "A study of chronic skin inflammation reveals that hyperactivation of PARP1 in response to ROS-induced DNA damage, fueled by NAMPT-derived NAD+, mediates skin inflammation via parthanatos cell death, identifying NAMPT, PARP1 and AIFM1 as novel therapeutic targets for psoriasis." (PMID 34748530, 2021). "Similarly, inhibition of NAMPT, PARP, and AIFM1 reduced the transcript levels DEFB4 and S100A8, another inflammation marker associated with psoriasis, while all treatments further reduced LOR and FLR mRNA levels, as did all-trans retinoic acid (ATRA)." (PMID 34748530, 2021). "Transcriptomic data revealed strong increased mRNA levels of PARP1, AIFM1, and MIF in psoriasis lesional skin." (PMID 34748530, 2021). "Consistent with this, clinical data support the alteration of NAD+ and PAR metabolism in psoriasis, pointing to NAMPT, PARP1, and AIFM1 as novel therapeutic targets to treat skin inflammatory disorders." (PMID 34748530, 2021).
Sensorineural deafness (2 papers, 2023 to 2024). "In conclusion, genes distribution of AN, with the most common genes being OTOF and AIFM1, is totally different from other sensorineural hearing loss." (PMID 38456936, 2024).
Sepsis (2 papers, 2020 to 2023). Sepsis is defined as life-threatening organ dysfunction caused by a dysregulated host response to infection. "In the report, TCONS_00016233 overexpression worsened sepsis-induced mouse AKI by down-regulating miR-22-3p, thus increasing the miR-22-3p target, apoptosis-inducing factor mitochondrion-associated 1 (AIFM1), leading to apoptosis." (PMID 37761260, 2023).
alopecia (1 paper, 2021). Hair loss usually from the scalp. "Our data suggest that the proviral insertion in the Aifm1 gene of the Hq mutant mice suppresses Aifm1 expression and might interfere with transcriptional programs involved in hair shaft development, possibly contributing to Hq-associated alopecia." (PMID 33367954, 2021). "Thus, Aifm1 down-regulation by the Hq mutation in the hair follicle causes alopecia by increasing the fragility of the subapical hair cortex and hence is distinct from the nude and related phenotypes." (PMID 33367954, 2021). "We hypothesized that this might lead to exacerbated alopecia in Aifm1(R200 del)/Hq females compared to Aifm1Hq/X heterozygous females." (PMID 33367954, 2021). "In this regard, the spontaneously arisen Harlequin (Hq) mutation was first described as an X-linked mutation causing complete alopecia in hemizygous males, which was subsequently found to be associated with an endogenous ecotropic retrovirus (ERV) integration into the Aifm1 gene." (PMID 33367954, 2021).
and peripheral sensory neuropathy (1 paper, 2015). "After Sanger sequencing and genotyping in all available family members, the only variant segregating with the phenotype (auditory and peripheral sensory neuropathy) of family 0223 was c.1030C>T (p.L344F) in the AIFM1 gene." (PMID 25986071, 2015).
Arthritis (1 paper, 2024). Inflammation of a joint. "AIFM1 has been reported to promote apoptosis in arthritis and IDD." (PMID 39717265, 2024).
COVID-19 (1 paper, 2025). A disease caused by infection with severe acute respiratory syndrome coronavirus 2. "We previously identified IgG autoantibodies targeting epitopes within brainstem proteins—disabled homolog 1 (DAB1), apoptosis-inducing factor 1 (AIFM1), and surfeit locus protein 1 (SURF1)—as markers of severe acute COVID-19." (PMID 40995367, 2025).
dilated cardiomyopathy (1 paper, 2021). Cardiomyopathy which is characterized by dilation and contractile dysfunction of the left and right ventricles. "A couple of cardiac studies demonstrated that loss of Aifm1 leads to severe dilated cardiomyopathy in mice, mitochondrial dysfunction, and increased oxidative stress in cardiomyocytes." (PMID 34200203, 2021).
Encephalopathy (1 paper, 2025). Encephalopathy is a term that means brain disease, damage, or malfunction. "In AIFM1-associated encephalopathies, mutations in the FAD-binding domain lead to protein instability, misvocalization, and mitochondrial dysfunction." (PMID 40963932, 2025). "In diseases linked to FAD deficiency or disrupted riboflavin metabolism, like L-2-HGA and AIFM1-related encephalopathy, aberrant chromatin states and DNA methylation patterns have been observed, underscoring a tight connection between riboflavin availability and gene expression regulation." (PMID 40963932, 2025).
hypomyelinating leukodystrophy (1 paper, 2017). "An X-linked condition characterized by the combination of hypomyelinating leukodystrophy and spondylometaphyseal dysplasia (H-SMD) has been observed in only four families, with linkage to Xq25-27, and recent genetic characterization in two families with a common AIFM1 mutation." (PMID 28842795, 2017).
hypospadias (1 paper, 2020). Hypospadias is the displacement of the urethral meatus on the ventrum of the penis. "AIFM1, which has also been found downregulated in the hypospadias group, is a pro-apoptotic factor in the caspase-independent pathway, which, in response to apoptotic stimuli, is released from the mitochondrial intermembrane space into the cytosol and to the nucleus." (PMID 33425810, 2020).
non-syndromic hearing loss (1 paper, 2021). "To date, five X-linked genes have been found to be related to the etiology of non-syndromic hearing loss (NSHL): PRPS1 (DFNX1, OMIM:311850), POU3F4 (DFNX2, OMIM:300039), SMPX (DFNX4, OMIM:300226), AIFM1 (DFNX5, OMIM:300169) and COL4A6 (DFNX6, OMIM:303631)." (PMID 33860785, 2021).
osteoarthritis (1 paper, 2024). A noninflammatory degenerative joint disease occurring chiefly in older persons, characterized by degeneration of the articular cartilage, hypertrophy of bone at the margins and changes in the synovial membrane. "For instance, silencing miR-766-3p, which promotes chondrocyte apoptosis in osteoarthritis, can be reversed by silencing AIFM1." (PMID 39717265, 2024).
pemphigus (1 paper, 2025). Pemphigus is a group of rare autoimmune diseases that cause blistering of the skin and mucous membranes (mouth, nose, throat, eyes, and genitals).This conditioncan occur at any age, but often strikes people in middle or older age. "Differential expression analysis was conducted to investigate the expression patterns of the five genes (XBP1, FBXO45, SAT2, AIFM1, and ACSL4) and eight other DEGs associated with ferroptosis (G3BP1, WBP11, TET2, IRF8, FASN, GDPD5, H1-4, and HUWE1) in both the pemphigus and control groups." (PMID 40612574, 2025).
skin aging (1 paper, 2021). The gradual irreversible changes in structure of skin that occur as a result of the passage of time.. "The TF E2F7 was also regulated by protein AIFM1 to downregulate target gene APAF1 in both young-adult and middle-aged skin aging." (PMID 34073305, 2021).
systemic lupus erythematosus (1 paper, 2025). An autoimmune multi-organ disease typically associated with vasculopathy and autoantibody production. "AIFM1 and PDK4 were notably enriched in pathways related to the cell cycle, complement and coagulation cascades, as well as systemic lupus erythematosus (SLE)." (PMID 40375928, 2025).
cancer (44 papers, 2009 to 2025). A tumor composed of atypical neoplastic, often pleomorphic cells that invade other tissues. "In mitochondrial oxidative stress diseases and cancer, AIFM1 is linked to apoptosis and cancer progression." (PMID 39717265, 2024). "The results obtained in this study showed a significant increase in mRNA expression of the gene encoding the AIFM1 protein in cancer cells of both lines as a result of the action of digested juice from young shoots." (PMID 37108053, 2023). "Both cell death and OXPHOS processes have been involved in cancer pathogenesis, but the role of AIFM1 during UC-associated carcinogenesis needs further investigation." (PMID 33987007, 2021). "This study identifies an effector complex involved in regulating the programmed cell death that accommodates the metabolic changes in the cell and provides a molecular explanation for AIFM1-mediated chemoresistance of cancer cells." (PMID 40055465, 2025). "Furthermore, high AIFM1 expression was related to better outcome, while reduced expression resulted in poorer patient OS across multiple cancer types." (PMID 40806359, 2025).
tumor (38 papers, 2011 to 2026). "Compared to the control group, the tumor group exhibited higher positive expression of AIFM1, AKT3, and IL1RAP." (PMID 40324259, 2025). "Aifm1 levels can be reduced, leading to abnormal cell survival, as observed in some human tumor types, but also increased, like in the case of hypoxic damage." (PMID 30394012, 2018). "Notably, excised tumor tissue from HT-29 xenografts demonstrated dephosphorylation of AIFM1 at Ser116 in SNG-treated mice, which is indicative of oxeiptosis." (PMID 36914635, 2023). "In addition, both CM presented a remarkable quantity of different proteins that have been associated with antioxidant and/or anti-inflammatory effects and may thus mediate the viability of non-tumor cells, such as AIFM1, ANXA5, CD9, CDH13, GDF15, GSR and TIMP2." (PMID 34884877, 2021).
infection (15 papers, 2011 to 2025). The state of being infected such as from the introduction of a foreign agent such as serum, vaccine, antigenic substance or organism. "Consistent with constrained necroptosis execution, MLKL expression remained minimal throughout infection, while AIFM1 decreased progressively, confirming parthanatos suppression." (PMID 41568347, 2025).
mitochondrial disease (4 papers, 2022 to 2025). "Moreover, Hq mice are considered as a relevant model of recessive X-linked mitochondrial disease due to AIFM1 mutations because of the nearly complete absence of the mitochondrial protein AIF33 in all their tissues." (PMID 38796706, 2024).
peripheral neuropathy (4 papers, 2019 to 2024). A disorder affecting the peripheral nervous system. "Three members of a family presenting with a complex syndrome (cerebellar ataxia and atrophy, mood and behavioural disorder, intellectual disability with or without hearing loss or peripheral neuropathy), were found to carry the p.G399S mutation in the NADH binding domain of AIFM1." (PMID 34356047, 2021).
nervous system diseases (3 papers, 2015 to 2021). "Recently, many studies have focused on the relationship between AIFM1 and nervous system diseases." (PMID 26075220, 2015).
myopathy (2 papers, 2021). A disease of the muscle in which the muscle fibers do not function properly. "Compared to Hq mutant mice, Aifm1(R200 del) knockin mice develop early-onset myopathy, however, they do not exhibit obvious neurological symptoms or hair loss, despite that across organs AIF protein levels are comparable between Aifm1(R200 del) KI and Hq mutant tissues." (PMID 33367954, 2021).
AIFM1 also shares sentences with these, for which no sentence is quoted: glioma (16 papers); Cerebral ischemia (8); lung cancer (8); prostate carcinoma (8); colon carcinoma (7); virus infection (5); diabetes (4); glioblastoma (4); pancreatic cancer (4); retinal degeneration (4); brain injury (3); cardiac ischemia (3); cervical carcinoma (3); ischemic stroke (3); neurodegenerative disease (3); ovarian carcinoma (3); adenoma (2); autosomal dominant optic atrophy (2); breast adenocarcinoma (2); Charcot-Marie-Tooth (CMT) disease (2); endometrial cancer (2); Ewing sarcoma (2); heart failure (2); Hypertension (2); injury (2); kidney tumor (2); liver cancer (2); lung adenocarcinoma (2); multiple myeloma (2); neuroblastoma (2).
A further 84 diseases each share a sentence with AIFM1 in 2 papers or fewer.